MACROH2A1 (macroH2A.1 histone)
Description:
Variant histone H2A which replaces conventional H2A in a subset of nucleosomes where it represses transcription. Nucleosomes wrap and compact DNA into chromatin, limiting DNA accessibility to the cellular machineries which require DNA as a template. Histones thereby play a central role in transcription regulation, DNA repair, DNA replication and chromosomal stability. DNA accessibility is regulated via a complex set of post-translational modifications of histones, also called histone code, and nucleosome remodeling. Involved in stable X chromosome inactivation. Inhibits the binding of transcription factors, including NF-kappa-B, and interferes with the activity of remodeling SWI/SNF complexes. Inhibits histone acetylation by EP300 and recruits class I HDACs, which induces a hypoacetylated state of chromatin. [Isoform 1]: Isoform that specifically binds poly-ADP-ribose and O-acetyl-ADP-ribose and plays a key role in NAD(+) metabolism. Able to bind to the ends of poly-ADP-ribose chains created by PARP1 and cap them (By similarity). This prevents PARP1 from further addition of ADP-ribose and thus limits the consumption of nuclear NAD(+), allowing the cell to maintain proper NAD(+) levels in both the nucleus and the mitochondria to promote proper mitochondrial respiration (By similarity). Increases the expression of genes involved in redox metabolism, including SOD3. [Isoform 2]: In contrast to isoform 1, does not bind poly-ADP-ribose. Represses SOD3 gene expression.
Synonyms: mH2A1; H2A/y; H2AFY; macroH2A1.2; H2A.y; H2AF12M; MACROH2A1.1
Tractability: Small molecule: a structure with a bound ligand is known; it has a high-quality binding pocket. PROTAC: UniProt records ubiquitination sites on it; ubiquitination databases record sites on it.
Gene: Protein-coding gene on chromosome 5 (135,333,609 to 135,400,023, reverse strand). Ensembl gene ENSG00000113648.
Subcellular location: Nucleus; Chromosome
Subcellular location (Human Protein Atlas): Nucleoplasm
Gene Ontology:
Molecular function: chromatin DNA binding; double-stranded methylated DNA binding; enzyme binding; nucleosomal DNA binding; protein binding; protein kinase binding; protein serine/threonine kinase inhibitor activity; rDNA binding; RNA polymerase II transcription regulatory region sequence-specific DNA binding; structural constituent of chromatin; transcription cis-regulatory region binding; DNA binding; poly-ADP-D-ribose modification-dependent protein binding; promoter-specific chromatin binding; ADP-D-ribose modification-dependent protein binding; chromatin binding; protein heterodimerization activity
Biological process: DNA repair; dosage compensation by inactivation of X chromosome; epigenetic regulation of gene expression; establishment of protein localization to chromatin; negative regulation of cell cycle G2/M phase transition; negative regulation of gene expression, epigenetic; negative regulation of protein localization to chromosome, telomeric region; negative regulation of transcription by RNA polymerase II; negative regulation of transcription of nucleolar large rRNA by RNA polymerase I; positive regulation of endodermal cell differentiation; positive regulation of keratinocyte differentiation; positive regulation of maintenance of mitotic sister chromatid cohesion; regulation of lipid metabolic process; regulation of rDNA heterochromatin formation; regulation of response to oxidative stress; transcription initiation-coupled chromatin remodeling; heterochromatin formation; nucleosome assembly; regulation of NAD metabolic process; regulation of oxidative phosphorylation
Cellular component: Barr body; chromatin; chromosome; chromosome, telomeric region; extracellular exosome; nuclear chromosome; nucleolus; nucleoplasm; nucleus; pericentric heterochromatin; site of DNA damage; nucleosome; sex chromatin; condensed chromosome
Genetic constraint (gnomAD): Loss-of-function variants: 0 observed, 19.33 expected, observed/expected ratio (o/e) 0, 90% interval 0 to 0.15. The upper end of that interval is the gene's LOEUF score, 0.15, which puts it in group 1 of 6, group 1 being the genes least tolerant of losing a copy. Missense variants: 181 observed, 389.91 expected, observed/expected ratio (o/e) 0.46, 90% interval 0.41 to 0.52. Synonymous variants: 142 observed, 160.93 expected, observed/expected ratio (o/e) 0.88, 90% interval 0.77 to 1.01.
Homologues: Orthologues: chimpanzee MACROH2A1 (100% identical), macaque MACROH2A1 (99% identical), pig MACROH2A1 (99% identical), guinea pig MACROH2A1 (99% identical), rat Macroh2a1 (98% identical), tropical clawed frog macroh2a1 (92% identical), mouse Macroh2a1 (91% identical), rabbit MACROH2A1 (88% identical), zebrafish macroh2a1 (70% identical), dog MACROH2A1 (51% identical), Drosophila melanogaster His2A:CG31618 (22% identical), Drosophila melanogaster His2A:CG33808 (22% identical), and 18 more. Paralogues in human: MACROH2A2 (68% identical), H2AC18 (23% identical), H2AC19 (23% identical), H2AC20 (23% identical), H2AC21 (23% identical), H2AC1 (23% identical), H2AC25 (23% identical), H2AC6 (23% identical), H2AC11 (22% identical), H2AC12 (22% identical), H2AC13 (22% identical), H2AC14 (22% identical), and 15 more.
Diseases named in the same sentence as MACROH2A1 in open-access papers:
MACROH2A1 is named in the same sentence as 62 diseases in open-access papers, as found by Europe PMC text mining. Sharing a sentence is not in itself a finding about the gene and the disease. The quoted sentences say what the papers report.
breast carcinoma (18 papers, 2014 to 2025). "In breast cancer cells, the tumor-promoting function was associated with macroH2A1.2 while macroH2A1.1 showed the opposite functions." (PMID 34203934, 2021). "Prognostically, low expression of macroH2A1.1 and macroH2A2 is associated with poor prognosis in several cancers such as lung, colorectal and breast cancer and astrocytoma." (PMID 34203934, 2021). "We investigated the relative expression levels of histone macroH2A1 splice variants and correlated it with breast cancer status/prognosis/types." (PMID 24911873, 2014). "Finally, mH2A and its isoforms are tumor suppressors- the loss of mH2A correlates in more aggressive cancer phenotypes and low expression of macroH2A1.1 is associated with poor prognosis in multiple cancers (colorectal, lung, astrocytoma, and breast cancers)." (PMID 39416124, 2024). "Besides breast cancer, macroH2A1 also showed diagnostic and prognostic value in HCC and lung cancer recurrence." (PMID 38542118, 2024). "Moreover, a histone variant consisting of C-terminal macro domain-MacroH2A1 was confined with breast cancer with worst prognosis and high risk of metastasis, which was same with HER2+ neoplasms." (PMID 35321515, 2022). "To detect differential expression of macroH2A1 variant mRNAs in breast cancer cells and tumor samples, we used the following databases: GEO, EMBL-EBI and publisher databases (may-august 2012)." (PMID 24911873, 2014). "Impaired macroH2A1.1 splicing, a frequent cancer feature, was predictive of increased sensitivity to TOP1 poisons in a pharmaco-genomic screen in breast cancer cells, and macroH2A1.1 inactivation mirrored this effect." (PMID 40796804, 2025). "A similar effect was observed in SKOV3 ovarian cancer cells, demonstrating that macroH2A1.1-mediated TOP1cc resistance is not limited to breast cancer cells." (PMID 40796804, 2025). "It is known that macroH2A1 and isoforms’ expression levels are usually high in different breast cancer types with worst prognosis." (PMID 38542118, 2024). "To determine the underlying molecular mechanisms, we mapped the genome-wide localization of endogenous macroH2A1.1 in the human breast cancer cell line MDA-MB-231." (PMID 35362516, 2022). "In conclusion, the immunohistochemical expression of macroH2A1 was more highly expressed in breast cancer with presence of metastases, finding that macroH2A1 is more highly expressed in breast cancer with poorer prognosis." (PMID 32974186, 2020). "While similar levels of macroH2A1 isoforms are expressed in normal adult cells, in breast cancer macroH2A1.1 expression tends to reduce and macroH2A1.2 is the predominant form." (PMID 32974186, 2020). "We investigated immunohistochemical expression of macroH2A1 in primitive breast cancer and metastases." (PMID 32974186, 2020). "In particular, recent studies have reported the role of macroH2A1.2 in negatively regulating breast cancer-induced osteoclastogenesis." (PMID 32974186, 2020). "Furthermore, the immunohistochemical expression of macroH2A1 was highly expressed in the metastases in almost all cases; thus, the immunohistochemical expression of macroH2A1 could predict the risk of breast cancer metastasis and thus directing strategies for follow-up and treatment of patients." (PMID 32974186, 2020). "We provide evidence that overexpression of macroH2A1.1 correlates with major mesenchymal markers of the claudin-low breast cancer subtype." (PMID 24911873, 2014). "Interestingly, induction of a battery of serum starvation genes in breast cancer cells, normally bound by macroH2A1, is inhibited by knockdown of macroH2A1." (PMID 29206173, 2017). "Ectopic macroH2A1 over-expression reduces the metastatic potential of melanoma and hepatocellular carcinoma (HCC), whereas macroH2A1 depletion increases the aggressiveness of HCC, teratoma, and breast cancer cells." (PMID 31096699, 2019).
breast carcinoma (continued). "Likewise, macroH2A1.2 was shown to cooperate with EZH2 to establish and maintain a repressive chromatin mark at the locus of the breast cancer-induced osteoclastogenic factor lysyl oxidase (LOX)." (PMID 34203934, 2021). "MacroH2A1 has two splice isoforms, macroH2A1.1 and macroH2A1.2, that have been studied in several form of cancer, but in breast cancer the function of macroH2A1 has not been much evaluated." (PMID 32974186, 2020). "In the literature there are not many scientific papers dealing with the role of macroH2A1 in breast cancer." (PMID 32974186, 2020). "We investigated immunohistochemical expression of macroH2A1 in primitive breast cancer, focusing on the comparison of metastatic and non-metastatic cases." (PMID 32974186, 2020). "Artificial over-expression of macroH2A1 reduces the metastatic potential of melanoma and hepatocellular carcinoma (HCC), whereas small interfering RNA (siRNA)-mediated depletion of macroH2A1 was shown to increase the aggressiveness of HCC, teratoma and breast cancer cells." (PMID 29206173, 2017). "Genome-wide occupancy studies demonstrated that, in quasi-physiological settings varying from starvation of breast cancer cells to adipocyte differentiation, macroH2A1 isoforms do not undergo a significant redistribution on chromatin positioning upon nutritional and differentiation cues." (PMID 29206173, 2017).
hepatocellular carcinoma (16 papers, 2013 to 2025). A malignant tumor that arises from hepatocytes. "Knockdown of macroH2A1, an epigenetic regulatory histone variant, in hepatocellular carcinoma cells promoted chemoresistance and CD4+CD25+FOXP3+ Treg cell activation." (PMID 39232704, 2024). "Rationale: Loss of histone macroH2A1 induces appearance of cancer stem cells (CSCs)-like cells in hepatocellular carcinoma (HCC)." (PMID 31903159, 2020). "Similarly, in hepatocellular carcinoma, increased Tregs following macroH2A1 loss correlate with chemoresistance." (PMID 41394821, 2025). "Similarly, the loss of macroH2A1 in hepatocellular carcinoma cells increases CD4+CD25+FOXP3+ Tregs, promoting chemoresistance and immune evasion." (PMID 41394821, 2025). "We found that loss of macroH2A1 resulted in significantly less heterochromatin visible in the nuclear periphery by TEM in HFF cells, similar to what was observed in hepatoma cells." (PMID 37516914, 2023). "High expression of macroH2A1 was observed in hepatocellular carcinoma (HCC), triple-negative breast cancer, colon cancer, lymphomas and the uveal subtype of melanoma." (PMID 34203934, 2021). "By performing detailed analyses in hepatoma cell lines, authors revealed that down-regulation of macroH2A1 can induce CSC properties, such as increased expression of stemness genes, resistance to chemotherapeutic agents, higher tumorigenicity, and induction of stem-like metabolic changes." (PMID 31349670, 2019). "We and others have shown that macroH2A1.1 ectopic expression sustains SASP in fibroblasts and hepatoma cells; a similar signaling loop might take place in the adipose tissue." (PMID 27800025, 2016).
melanoma (13 papers, 2013 to 2024). A malignant, usually aggressive tumor composed of atypical, neoplastic melanocytes. "Genetic depletion of CDK8 in macroH2A1-deficient melanoma cells attenuated the proliferative advantage related to loss of macroH2A1." (PMID 34203934, 2021). "Loss of all macroH2A1 isoforms, positively correlated with increasing malignant phenotype of melanoma cells both in cell lines, in human tissue samples, and in animal models of cutaneous melanoma growth and metastasis; this phenotype could be restored by reintroduction of macroH2A1." (PMID 32401230, 2020). "Examining human melanoma-derived primary CAF cultures revealed homogenous levels of macroH2A1 protein, whereas macroH2A2 spanned almost an order of magnitude." (PMID 37605008, 2023). "MacroH2A1, present throughout normal skin, was retained in melanomas, whereas macroH2A2, detected primarily at low levels in the hair follicle in normal skin, was focally present in the tumour." (PMID 37605008, 2023). "In contrast, high expression of macroH2A1 induced G2/M cell cycle arrest in melanoma and osteosarcoma cells." (PMID 34203934, 2021). "Gene expression profiling of melanoma B16-F61 cells also found that decreased macroH2A1 levels correlate with a ≥2-fold change in the expression of cyclin-dependent kinase 8 (CDK8), a CRC oncogene." (PMID 31096699, 2019). "Immunohistochemical analyses of melanoma tissues have shown a decrease in macroH2A1 mRNA levels compared to control tissues." (PMID 31096699, 2019). "Other studies, which did not distinguish between the isoforms, demonstrated that KO of all macroH2A1 isoforms induced the progression of the melanoma malignant phenotype both in vitro and in vivo through increased expression of CDK8 oncogene." (PMID 23372727, 2013). "In both in vivo and in vitro experiments, reducing the expression level of MacroH2A1.2 could promote the progression of melanoma by increasing the expression of the CDK8 oncogene." (PMID 33858382, 2021). "Other evidences support a tumour suppressive role of macroH2A1.2 in melanoma and bladder cancer, suggesting that macroH2A1.2 function might be strongly context-dependent." (PMID 29495465, 2018). "Moreover, when macroH2A1 was down regulated, global decondensation of chromatin structure can be detected with Micrococcal nuclease (MNase) assay, consistent with the results observed in melanoma cells." (PMID 26603343, 2015).
colon cancer (7 papers, 2014 to 2024). "Concerning MacroH2A1.1 expression, the same has been reported for other carcinomas, being its loss associated with worse outcome in colon cancer patients." (PMID 31164793, 2019). "While in lung and colon cancer macroH2A1.1 loss is a marker of poor prognosis, it is interesting that the opposite association exists for triple-negative breast cancer, where macroH2A1.1 expression is a marker of poor prognosis." (PMID 31636161, 2019). "A downregulation of macroH2A1.1 and an elevated expression of macroH2A1.2 are detected in colon cancer." (PMID 39199381, 2024). "In colon cancer patients, MacroH2A1.1 mRNA expression was decreased, while MacroH2A1.2 mRNA expression was up-regulated." (PMID 33858382, 2021). "Knockdown of macroH2A1.1 promotes tumor cell growth and proliferation in colon cancer." (PMID 39199381, 2024). "MacroH2A1 isoforms are thus highly expressed in cells undergoing senescence, which is an antitumor mechanism, suggesting macroH2A1, and in particular macroH2A1.1, may be a useful biomarker for senescent cells in tumors such as lung and colon cancer." (PMID 29206173, 2017). "Notably, expression of macroH2A1.1 has been identified as a novel biomarker in lung and colon cancer models." (PMID 24911873, 2014).
steatosis (6 papers, 2010 to 2023). Increased lipid within the cytoplasm of cells. "To determine the molecular cause of the sexual dimorphism of the steatosis promoted by H2afy disruption, we compared macroH2A1 levels on the Tbg promoter in male versus female animals." (PMID 20359320, 2010). "Interestingly, wild-type mice fed a lipogenic diet poor in methyl groups (methionine/choline-deficient diet), which induces liver steatosis and inflammation, show an increase in the total liver content of macroH2A1." (PMID 34440260, 2021). "As observed in macroH2A1 KO mice, NAFLD is associated with the development of a spectrum of liver damage, including carcinogenesis, and steatosis-associated HCC is histologically featured by immunopositivity for histone macroH2A1 isoforms marks." (PMID 34440260, 2021). "We assessed if the protein expression levels of macroH2A1.1 and macroH2A1.2 were altered in the context of steatosis or HCC in liver specific PTEN KO mice." (PMID 23372727, 2013). "Notably, the downregulation of macroH2A1.2 was nearly twice as significant as that of macroH2A1.1 in lean patients with steatosis grade 3 compared with those with grade 1." (PMID 37629043, 2023). "Similarly to the HF/DEN model, in the PTEN KO model of steatosis and HCC both macroH2A1 isoforms associate with cancer, whereas macroH2A1.2 is specifically upregulated in the fatty liver." (PMID 23372727, 2013). "Thus, in the HF/DEN dietary model of steatosis and HCC, both macroH2A1 isoforms were associated with cancer, whereas macroH2A1.2 is specifically increased in the presence of fat." (PMID 23372727, 2013). "Immunopositivity for both macroH2A1 isoforms were markedly upregulated in HCC, whereas macroH2A1.2 was specifically upregulated in steatosis." (PMID 25195642, 2014). "Protein levels for both macroH2A1 isoforms were massively upregulated in HCC, whereas macroH2A1.2 was specifically upregulated in steatosis." (PMID 23372727, 2013). "mRNA levels for macroH2A1.1 and macroH2A1.2 in the animal models and in liver biopsies from patients were variable and did not reflect the differences observed in the protein levels found in steatosis and HCC (data not shown)." (PMID 23372727, 2013). "Furthermore, we examined the expression of macroH2A1 isoforms in human liver biopsies from patients where HCC occurred in a background of pure steatosis, in absence of other liver diseases." (PMID 23372727, 2013). "Hence, we conclude that the absence of macroH2A1 induces steatosis." (PMID 20359320, 2010).